IL27 (interleukin 27)
Diseases named in the same sentence as IL27 in open-access papers (continued):
Sharing a sentence is not in itself a finding about the gene and the disease.
Sepsis (continued). "Since the spleen is a known site for IL-27 expression during neonatal sepsis that correlates with a high bacterial burden in WT neonates, we profiled the transcriptome of this tissue." (PMID 36891292, 2023). "Recently, we established a murine neonatal model of Escherichia coli O1:K1:H7-induced sepsis to explore the impact of early life IL-27 levels on the host response to infection." (PMID 36891292, 2023). "This study elucidated that ADMSC-exosomes protected mice against sepsis-induced ALI by inhibiting the secretion of IL-27 in macrophages." (PMID 35013123, 2022). "Briefly, we were the first to demonstrate that ADMSC-exosomes retarded sepsis-induced ALI by mediating the secretion of IL-27." (PMID 35013123, 2022). "Collectively, ADMSC-exosomes inhibited IL-27 secretion in macrophages and alleviated sepsis-induced ALI in mice." (PMID 35013123, 2022). "In contrast, other studies reported that IL-27 blockade increased the severity of sepsis-induced myocardial dysfunction in an endotoxic shock syndrome murine model." (PMID 36028492, 2022). "Previous studies have shown that serum IL-27 levels are elevated in sepsis patients, indicating the potential of this cytokine as a diagnostic biomarker for sepsis." (PMID 36028492, 2022). "IL-27 neutralizing antibody therapy can reduce pulmonary inflammation and alleviate ALI caused by sepsis." (PMID 35013123, 2022). "IL-27 expression in patients with sepsis and septic mice is notably increased and closely related to the severity and mortality of sepsis." (PMID 35013123, 2022). "Injection of recombinant IL-27 reversed the protective effect of exosomes on sepsis-induced lung injury." (PMID 36016948, 2022). "Although IL-27 has the potential for clinical applicability for identifying sepsis in critical patients, the test results of IL-27 should be explained in combination with clinical and other test factors." (PMID 33954170, 2021). "In conclusion, IL-27 can be used as a candidate biomarker for the diagnosis of patients with sepsis." (PMID 33954170, 2021). "All studies published up to October 21, 2020, which evaluated the accuracy of IL-27 levels for the diagnosis of sepsis were included." (PMID 33954170, 2021). "have showed that EBI3, a subunit of IL-27, had the highest predictive strength for patients with sepsis among the 221 differentially regulated gene probes." (PMID 34079555, 2021). "A previous study has shown that the average IL-27 levels in the plasma of children with sepsis are higher than those in adults because the upregulation of IL-27 expression in answer to infection is more robust in children." (PMID 33954170, 2021). "Several studies have also demonstrated that IL-27 is a beneficial cytokine that can prevent sepsis-induced myocardial dysfunction and death." (PMID 34079555, 2021). "Prior studies using a murine sepsis model induced by subcutaneously injected Escherichia coli demonstrated that IL-27 blockade improves the survival rate." (PMID 34079555, 2021). "As an inflammatory cytokine, IL-27 plays an important role in infection disease, promotes the inflammatory response of sepsis, and acts as a marker in predicting bacterial infection in critically ill children." (PMID 33564275, 2021). "In our meta-analysis, the calculated DOR was 15 (95% CI, 3-72), suggesting a high overall accuracy of IL-27 as a biological marker for differential diagnosis of sepsis." (PMID 33954170, 2021). "In animal experiments, neutralizing the biological function of IL-27 improves the survival time of mice with sepsis." (PMID 33954170, 2021). "In contrast, our findings demonstrate that IL-27 indirectly promotes an inflammatory cytokine response during neonatal sepsis by directly compromising control of bacteria that drive the inflammatory response." (PMID 31818960, 2020). "In the present body of work, we examined the impact of IL-27 on host protection during neonatal sepsis." (PMID 31818960, 2020).
Sepsis (continued). "In a mouse model of polymicrobial sepsis that was induced by cecal ligation and puncture, multiple IL-27-mediated consequences have been documented." (PMID 32802395, 2020). "The plasma concentration of IL-27 is significantly elevated in murine models of sepsis, as well as in human patients with this condition; accordingly, it is considered to be a potential diagnostic marker for sepsis." (PMID 33276561, 2020). "In mice, the results are more consistent and indicate a clear role for IL-27 in the pathology of sepsis and critical illness." (PMID 31507598, 2019). "Recent evidence links interleukin (IL)-17, IL-27, and IL-33 to alterations in the immune response during sepsis using patient serum and murine models of peritonitis and pneumonia." (PMID 31507598, 2019). "This review will describe how IL-17, IL-27, and IL-33 exert these effects during sepsis and their potential as therapeutic targets." (PMID 31507598, 2019). "In murine sepsis, IL-10 has been reported to suppress the expression of IL-27 by activated F4/80+CD11b+ macrophages in an STAT3-dependent pathway." (PMID 31214168, 2019). "Recent work on the cytokines IL-17, IL-27, and IL-33 suggest the presence of a novel cytokine axis during sepsis." (PMID 31507598, 2019). "Other studies have demonstrated that the neutralization of IL-27 decreases the inflammatory response and affords mice a survival benefit following sepsis." (PMID 30268141, 2018). "The rs153109 (− 964 A > G) promoter polymorphism of IL-27 may alter its gene transcription and cause alterations in the inflammatory responses, which ultimately result in the progression of sepsis from sepsis subtype to severe sepsis/septic shock and poor prognosis." (PMID 30268141, 2018). "Consistently, our data showed that IL-27 treatment significantly enhanced TNF-α and IL-6 secretion and apoptosis of THP-1 cells upon LPS stimulation, which further demonstrated that IL-27 is critical in the pro-inflammatory responses during sepsis." (PMID 30268141, 2018). "IL-35 levels were observed to display a positive correlation with the levels of other pro-inflammatory mediators released in sepsis (including; IL-6, IL-8, IL-27, TNF-α and IL-10)." (PMID 29641433, 2018). "Recent studies have indicated that IL-27 expression is significantly increased in patients with sepsis and in septic mice, and is strongly correlated with disease severity and mortality following sepsis." (PMID 30268141, 2018). "We further divided the patients with sepsis into subgroups of sepsis subtype, severe sepsis or septic shock, based on the severity of sepsis, to assess the effect of IL-27 SNPs on the development of sepsis." (PMID 30268141, 2018). "Enhanced expression of IL-27 has been identified in patients with sepsis and in a model of sepsis, which was closely correlated with disease severity and mortality." (PMID 30268141, 2018). "Previous research utilizing IL-10 and IL-27 (an IL-12 cytokine family member) in murine models of sepsis have yielded promising outcomes directed towards the understanding of cytokine dynamics in septic shock." (PMID 29641433, 2018). "We further measured the plasma concentrations of related pro-inflammatory cytokines in the selected 80 patients with sepsis and 80 healthy subjects to evaluate the effect of the IL-27 SNPs on the production of these cytokines." (PMID 30268141, 2018). "Our data suggest that both the transcriptional and translational levels of IL-27 were overexpressed in patients with sepsis, which corroborates several previous studies." (PMID 30268141, 2018). "When the data were stratified by genotype, our results suggested that the IL-27 mRNA levels in patients with sepsis carrying the AA genotype of rs153109 were significantly higher than those in patients with the GA/GG genotypes (P = 0.044)." (PMID 30268141, 2018).
Sepsis (continued). "The patients with sepsis were further stratified by 28-day mortality into two subgroups to evaluate the effect of IL-27 SNPs on the clinical outcome of patients with sepsis." (PMID 30268141, 2018). "Then, we detected the expression levels of IL-1β, IL-6 and TNF-α in patients with sepsis and healthy subjects to evaluate the influence of the functional IL-27 SNP on the production of these related cytokines." (PMID 30268141, 2018). "Previous genome-wide transcriptome profiling of whole blood samples derived from paediatric patients with SIRS, sepsis, or septic shock revealed putative use of circulating IL27 in the blood as a biomarker for sepsis in human patients." (PMID 28056766, 2017). "Patients with SIRS had significantly lower IL-27 serum protein concentrations compared with patients with sepsis and patients with septic shock." (PMID 23107287, 2012). "Previous studies have reported conflicting roles of IL-27 in sepsis and lung injury models." (PMID 41024268, 2025). "To understand the impact of IL-27 on regulation of the neonatal host response to infection, we previously analyzed the transcriptome of the neonatal spleen during K1-encapsulated E. coli-induced sepsis in WT and KO mice." (PMID 40977737, 2025). "In several studies, it has been suggested that IL-27 can serve as a marker of prognosis in sepsis." (PMID 39063193, 2024). "Moreover, elevated levels of Interleukin-27 (IL-27) in early life have been shown to compromise protective immunity in a mouse model of sepsis." (PMID 39469711, 2024). "IL-27 revealed the most superior validity in the detection of late-onset sepsis." (PMID 38027268, 2023). "In recent years, IL-27 has been used as a biological marker for sepsis diagnosis." (PMID 38027268, 2023). "To explore a reprogramming of the host response in the absence of IL-27 signaling, we profiled the transcriptome of the neonatal spleen during Escherichia coli-induced sepsis in wild-type (WT) and IL-27Rα-deficient (KO) mice." (PMID 36891292, 2023). "Studies have shown that the effect of IL-27 may be related to the pathogen that infects the bacteria, the host's immune status, and the duration of infection, a better understanding of pathogen specific IL-27 responses during sepsis may have clinical benefits." (PMID 38027268, 2023). "Recent study revealed that EVs from adipose-derived MSCs could alleviate sepsis-induced lung injury in mice by inhibiting the secretion of IL-27 in macrophages." (PMID 37711624, 2023). "In particular, adipose-derived MSC-derived EVs could inhibit IL-27 secreted from macrophages, which ameliorates sepsis-induced ALI in model mice." (PMID 36959535, 2023). "IL-27 is a cytokine that increases during sepsis, and its suppression could be a potential target in treating sepsis." (PMID 35682948, 2022). "The existing findings suggest that IL-27 inhibition may become a prospective therapeutic target for patients with sepsis-induced ALI." (PMID 35013123, 2022). "Although IL-27 has been shown to be elevated in sepsis, our apparently contradictory results could be explained by the fact that IL-27 has been shown to be overexpressed in rodent models of intracerebral hemorrhage." (PMID 35327327, 2022). "Interestingly, non-septic ICU patients showed higher plasma levels of IL-13 and IL-27 than the sepsis and the SS groups." (PMID 35327327, 2022). "Additionally, blockade of IL-27 was reported to improve mortality in mouse models of endotoxin- and sepsis-induced cytokine storms." (PMID 36148243, 2022). "Altogether, ADMSC-exosomes retarded sepsis-induced lung injury by limiting the secretion of IL-27." (PMID 35013123, 2022). "Recent evidence has indicated the crucial role of IL-27 in the pathogenesis of sepsis, and blocking IL-27 may be an alternative therapy for sepsis." (PMID 35013123, 2022). "Injection of recombinant IL-27 reversed the protective effect of ADMSC-exosomes on sepsis mice." (PMID 35013123, 2022).
Sepsis (continued). "Therefore, our meta-analysis included seven articles to investigate the value of IL-27 in diagnosing patients with sepsis." (PMID 33954170, 2021). "Moreover, the sub-set of the patients with sepsis had low levels of IL-27, which was reported to correlate with improved outcome." (PMID 34819932, 2021). "Better understanding of pathogen-specific IL-27 responses during sepsis could be clinically beneficial." (PMID 34079555, 2021). "In sepsis patients, IL-27 promoted the inflammatory response and aggravated liver damage." (PMID 32075272, 2020). "Furthermore, this review will address some of the clinical implications of IL-27 signaling among different pathological states in young and aged populations, including sepsis, tuberculosis, neurological diseases and HIV." (PMID 32802395, 2020). "In addition, IL-27 levels seem to be increased during sepsis, and at least in children, potentially giving prognostic information in these patients." (PMID 31964363, 2020). "We have established elevated levels of the immune-suppressive cytokine IL-27 at the resting state in neonates, and we further demonstrate here that those levels continue to rise in most neonatal pups following infection that leads to sepsis." (PMID 31818960, 2020). "We further investigated the impact of elevated IL-27 levels on survival during neonatal sepsis." (PMID 31818960, 2020). "In this review, we will further discuss the individual and combined roles of IL-17, IL-27, and IL-33 during sepsis and how this axis might be therapeutically targeted." (PMID 31507598, 2019). "However, mice can produce IL-27p28 in the absence of EBI3, so it is unclear if the reported effects of IL-27 during sepsis are actually due to the full heterodimeric cytokine or merely to its alpha subunit." (PMID 31507598, 2019). "Nonetheless, there are currently no studies exploring the genetic association of these IL-27 SNPs with sepsis, and the related mechanisms by which these variants influence systemic inflammatory responses upon sepsis remain to be elucidated." (PMID 30268141, 2018). "Nevertheless, the role of these IL-27 polymorphisms has not been determined in the pathogenesis of sepsis." (PMID 30268141, 2018). "Additionally, we detected the plasma concentration of IL-27 in these patients with sepsis and in controls using ELISA, which was consistent with the results from the gene expression analysis in PBMCs." (PMID 30268141, 2018). "In this study, 885 patients with sepsis and 1101 healthy subjects were examined to evaluate the clinical relevance of two IL-27 genetic SNPs, rs153109 (− 964 A > G) and rs17855750 (2905 T > G), in the susceptibility and progression of sepsis in a Han Chinese population." (PMID 30268141, 2018). "In our study IL-27 exerted a significant effect on the progression of sepsis and might also serve as an indicator of disease severity as it increased with the development of sepsis." (PMID 30268141, 2018). "Previous studies have identified critical roles of IL-27 in the pathological mechanisms of sepsis, and blockade of IL-27 may be a promising alternative therapy for sepsis." (PMID 30268141, 2018). "It has also recently been shown that IL-27 could be a predictive molecule of sepsis in children, and that the activated platelets could be a significant source of this cytokine." (PMID 25767472, 2015). "Notably, EBI3, a subunit of IL-27 has been recently unmasked as a potential sepsis biomarker by genome-wide expression profiling." (PMID 24236088, 2013). "Finally, the serum IL-27 data reflect the first 24 hours of meeting criteria for either SIRS or sepsis, which is a clinically relevant time point for the prediction of bacterial infection in critically ill patients." (PMID 23107287, 2012).
Sepsis (continued). "To determine the ability of serum IL-27 concentrations to predict bacterial infection in critically ill patients, we grouped the patients with sepsis and septic shock as positive cases for infection, and compared them with the SIRS patients as negative cases for infection." (PMID 23107287, 2012). "Collectively, the transcriptome of IL-27 producers from the livers of infected animals suggests an uncoordinated mix of inflammatory and suppressive activity that may contribute to immune dysregulation characteristic of sepsis." (PMID 40682363, 2025). "IL-27 encourages the production of naive CD4+ T cells and causes both pro-inflammatory and anti-inflammatory responses and according to some authors, it could be the representative biomarker for sepsis." (PMID 38152329, 2023). "Interestingly, several studies have reported elevated serum IL-27 levels during sepsis, suggesting that IL-27 could potentially be useful in predicting sepsis-driven mortality." (PMID 36028492, 2022). "Finally, we need to understand how IL-27 prevents cytokine storm and internal organ tissue damage during chronic S. aureus osteomyelitis in a more relevant murine model of osteomyelitis-induced sepsis." (PMID 36028492, 2022). "In this study, cytokines TNF, IL-6, IL-10, IFN-γ, IL-27, alarmins Hsp72 and Hsp90, and markers associated with inflammation (CRP, procalcitonin, lactate) and stress (glucose) exhibited early-onset induction, which was strongly correlated with an increased TOS/TAC ratio in sepsis." (PMID 35204114, 2022). "The sensitivity, specificity, and AUC of IL-27 in our study showed similarities with PCT (0.77, 0.79, and 0.85, respectively), IL-6 (0.73, 0.76, and 0.81, respectively), and presepsin (0.77, 0.73, and 0.86, respectively), which are valuable diagnostic markers for sepsis in published studies." (PMID 33954170, 2021). "Whether neutrophils produce the IL-27 complex or IL-30 during sepsis remains to be determined." (PMID 34045653, 2021). "Interestingly, blockade of IL-27 is beneficial against sepsis." (PMID 34079555, 2021). "Thus, 77 of 100 patients with positive IL-27 results could be expected to have a confirmed diagnosis of sepsis." (PMID 33954170, 2021). "However, another IL-27 polymorphism at rs17855750 G > T did not significantly affect sepsis susceptibility or progression." (PMID 30268141, 2018). "Significantly greater IL-27 mRNA levels were found in patients with sepsis relative to the controls (P < 0.0001), and expression significantly was significantly greater with the development of sepsis (P = 0.047 for severe sepsis and P = 0.042 for septic shock)." (PMID 30268141, 2018). "Thrombin formed during sepsis could lead to this release of platelet IL-27." (PMID 25767472, 2015). "Finally, it does not appear that increased IL-27 protein concentration in critically ill children with bacterial infection reflects increased illness severity, because the median IL-27 concentrations were similar between patients with sepsis and patients with septic shock." (PMID 23107287, 2012). "The signaling activity of IL‐27 through the IL‐27B (EBI3) receptor protein influences various immune cells, potentially contributing to the immune dysregulation seen in sepsis and SCM." (PMID 40396598, 2025). "Since proinflammatory cytokine overproduction is indicative of sepsis, we evaluated the levels of TNF‐α, IFN‐γ, IL‐1α, IL‐1ß, IL‐6, IL‐10, IFN‐ß, IL‐17A, IL‐23, IL‐27, MCP‐1, IL‐12p70, and GM‐CSF in the serum at 16 h after LPS‐induced septic shock." (PMID 39482884, 2025). "Increases in other cytokines such as IL-8 and IL-27 have been reported in several studies that enrolled children with sepsis, suggesting that their monitoring alone or in combination with other biomarkers may be of value in the evaluation of children with sepsis." (PMID 39858517, 2025).